PXN-AS1 (PXN antisense RNA 1)
Synonyms: EyeLinc4
Gene: Long non-coding RNA gene on chromosome 12 (120,201,260 to 120,213,401, forward strand). Ensembl gene ENSG00000255857.
Diseases named in the same sentence as PXN-AS1 in open-access papers:
PXN-AS1 is named in the same sentence as 7 diseases in open-access papers, as found by Europe PMC text mining. Sharing a sentence is not in itself a finding about the gene and the disease. The quoted sentences say what the papers report.
lung carcinoma (1 paper, 2019). "Remarkably, the list of genes included PXN-AS1, which was reported to interact with the nuclear-localized splicing factor MBNL3 to promote liver and lung cancer progression." (PMID 31781161, 2019).
tumor (2 papers, 2020 to 2022). "For instance, H-Ras, CD44, PXN-AS1, macroH2A1, etc., are important tumor-related factors; therefore, the dysregulation of DDX5/DDX17 action is closely related to tumorigenesis and tumor progression." (PMID 35992805, 2022). "PXN‐AS1 inhibition was also found to restrain GBM tumour growth." (PMID 32329150, 2020).
PXN-AS1 also shares sentences with these, for which no sentence is quoted: breast carcinoma (1 paper); cancer (1); colorectal cancer (1); gastric cancer (1); hepatocellular carcinoma (1).